IL15 (interleukin 15)
Diseases named in the same sentence as IL15 in open-access papers (continued):
Sharing a sentence is not in itself a finding about the gene and the disease.
Immunodeficiency (15 papers, 2011 to 2025). Failure of the immune system to protect the body adequately from infection, due to the absence or insufficiency of some component process or substance. "IL2RB-deficient patients show dysregulated IL2 and IL15 signaling, enhanced natural killer cell levels, and subsequent immunodeficiency and impaired antiviral immunity." (PMID 33633136, 2021). "Since γc is shared by receptors for IL-4, IL-7, IL-9, IL-15, and IL-21 and a loss of γc function causes immunodeficiencies in both humans and mice, it is anticipated that knockdown of γc may lead to severe systemic side effects." (PMID 24223832, 2013). "For that matter, IL-2 and IL-15 supplementation have been proposed as to improve the immune disorder and reduce mortality." (PMID 36238287, 2022). "Jak3 knockout mouse model showing Il-2, Il-4, Il-7, Il-9, and Il-15 conduction defects, elevated levels of Il-6 and Il-17a and severe immunodeficiency, defects in barrier function lead to Ulcerative colitis (UC)." (PMID 33777833, 2021). "The increased levels of IL-15 found in several CD4+ T cell-driven (auto-) immune diseases prompted us to examine how IL-15 influences murine CD4+ T cell responses to low dose TCR-stimulation in vitro." (PMID 23028916, 2012). "The current data suggest that insufficient IL-15 levels and decreased responsiveness of Tregs to IL-15 signaling might contribute to strong immune dysfunction in CHB patients with T2DM." (PMID 35801423, 2023). "Overall, insufficient IL-15 levels and decreased responsiveness of CD4+CD25+CD127dim/− Tregs to IL-15 signaling might contribute to the immune dysfunction in CHB patients with T2DM." (PMID 35801423, 2023). "Here, we describe a human immunodeficiency-like condition characterized by a reduced frequency of CD3−C56dim cells with lower percentages of terminally differentiated NK cells, and accumulation of CD3−CD56bright cells in peripheral blood that exhibit altered activation in response to IL-2 and IL-15." (PMID 23240056, 2012).
osteoarthritis (15 papers, 2011 to 2025). A noninflammatory degenerative joint disease occurring chiefly in older persons, characterized by degeneration of the articular cartilage, hypertrophy of bone at the margins and changes in the synovial membrane. "Finally, elevated IL-15 levels have been noted in age-associated osteoarthritis and very old individuals." (PMID 23385138, 2013). "Despite the fact that predominant pro-inflammatory cytokines such as IL-1β, TNF-α, IL-15, or IL-6 are well described in human medicine research, it is not documented which biomarker is the gold standard for evaluating osteoarthritis in animal species." (PMID 37443993, 2023). "Inhibited pathways included leukocyte extravasation signaling, IL-6 across the time course, IL-15 production and acute phase response signaling, key players in the development and maintenance of synovitis and degenerative processes observed in osteoarthritis." (PMID 34956173, 2021). "Increased levels of IL-15 were detected in serum, synovial fluid and bone marrow of RA patients compared to patients with other inflammatory arthropathies and/or osteoarthritis." (PMID 32455601, 2020). "Interleukin-15 was detected in 15 (83.3%) UA→RA patients, 11 (32.4%) UA→UA patients, one patient who developed osteoarthritis, and one patient who developed reactive arthritis." (PMID 32455601, 2020). "In osteoarthritis, many other cytokines (e.g., IL-6, TNF-α, IL-15) also play an important role during the progression of the disease." (PMID 35885038, 2022). "The aim of this work is to compare the expression profile of IL-15Ralpha, its ligand IL-15 and two validated cytokines targets in RA, TNF alpha and IL-6, in SF from RA regards to Osteoarthritis (OA) patients." (PMID 25879761, 2015). "Comparatively, glycoprotein 6 (z-score 5.48), IL-15 production (z-score 5.00), fibrosis (z-score 6.71) and epithelial-mesenchymal transition signaling (no z-score), and osteoarthritis (z-score 3.34) were identified in macrophages at 14 days." (PMID 39100672, 2024). "We now show, using BM samples obtained from persons who underwent hip replacement surgery because of osteoarthrosis, that senescent CD8+ TEMRA cells with a bright expression of CD45RA and a high responsiveness to IL-15 accumulate in the BM of CMV-infected persons." (PMID 28674537, 2017). "The aim of this work was to compare the expression profile of IL-15Ralpha, its ligand IL-15, TNFalpha and IL-6 and how these cytokines are correlated in SF from RA patients taking as a reference Osteoarthritis (OA), an articular but not autoinmmune disease." (PMID 25879761, 2015). "In support of its contribution to RA pathogenesis, IL-15 can be detected in the synovial fluid of inflamed joints in patients with RA but not in patients with osteoarthritis or other inflammatory joint diseases." (PMID 22242124, 2011). "Interleukin-15 (IL-15) is thought to be involved in the physiopathological mechanisms of RA and it can be detected in the serum and the synovial fluid of inflamed joints in patients with RA but not in patients with osteoarthritis or other inflammatory joint diseases." (PMID 22242124, 2011).
osteosarcoma (15 papers, 2019 to 2025). A usually aggressive malignant bone-forming mesenchymal neoplasm, predominantly affecting adolescents and young adults. "IL-15 activation significantly enhanced cytotoxicity, and osteosarcoma cells were susceptible to such NK cells activated by IL-15." (PMID 39916962, 2024). "He discovered that chemotherapy-resistant osteosarcoma is highly sensitive to IL-15-activated allogeneic and autologous NK cells, supporting the therapeutic potential of NK cells or NK cell activators in high-grade osteosarcoma patients." (PMID 40019638, 2025). "These two studies emphasized the application value of IL15, an NK cell-activating agent, in osteosarcoma." (PMID 35720360, 2022). "Nevertheless, TIM-3 was found to be expressed on NK cells, and anti-TIM-3 antibody in combination with a superagonist of IL-15 (ALT-803) enhanced NK cell cytotoxicity against osteosarcoma cells ex vivo." (PMID 34804076, 2021). "For example, in one study IL-15 stimulated NK cells targeted osteosarcoma predominantly through DNAM1, whereas in another study IL-2 stimulated NK cells targeted osteosarcoma predominantly through NKG2D." (PMID 34164452, 2021). "For instance, IL-15, the most promising NK cell-activating cytokine, can strongly enhance NK cell-mediated cytolytic activity toward chemotherapy-resistant osteosarcoma." (PMID 31156651, 2019). "used IL-15 activation of NK cells to enhance the ability of NK cells to kill osteosarcoma cells." (PMID 39916962, 2024). "The addition of immunomodulatory cytokines such as IL2, IL15, and liposomal-muramyl tripeptide phosphatidylethanolamine might induce T cell proliferation and differentiation to improve the survival outcomes of osteosarcoma patients, but the evidence is insufficient." (PMID 35720360, 2022). "Osteosarcoma had 25 significant relationships, notably including IL-4/IL-1β (r2 = 0.58, p = 0.000048), IL-12 p40/IL-4 (r2 = 0.47, p = 0.0015), CXCL5/IL-27 (r2 = −0.48, p = 0.001), CXCL14/IL-15 (r2 = 0.66, p = 0.0000021)." (PMID 41008853, 2025).
pneumonia (15 papers, 2012 to 2025). An acute, acute and chronic, or chronic inflammation focally or diffusely affecting the lung parenchyma, caused by an infection in one or both of the lungs (by bacteria, viruses, fungi, or mycoplasma.). "In robust inflammatory reactions, IL-15 is released as a result of cell death, which explains the high levels of this cytokine in the serum of patients with pneumonia." (PMID 37629892, 2023). "In particular, IL-15 responses were significantly higher in pneumonia patients (except P12) than group I patients." (PMID 27146253, 2016). "Relative to controls, cytokines that were significantly elevated in the pneumonia cohort at 24 and/or 48 h after inoculation (evolution phase) were IL‐1β, IL‐6, IL‐15, IL‐16, IL‐17a, IP‐10, MCP‐1, MIP‐1β, and TARC; IL‐5 was significantly elevated at 168 h (resolution phase)." (PMID 40947770, 2025). "In the next steps, IL-15, IL-6, pneumonia, and IL-12 were rejected." (PMID 39335569, 2024). "Pneumonia correlates with specific cytokines IFN2, Il-15, IL-7, sCD40L, MCP-1, FGF-2, MIP-1b, MIP-1a, MDC, and GM-CSF." (PMID 37629267, 2023). "Further, increases in IL-6, IL-8, IL-10, IL-15, TNF-α, and IFN-γ have been reported in severe pneumonia compared with mild pneumonia." (PMID 34692846, 2021). "For example, the concentrations of cytokines such as interleukin-6 (IL-6), interleukin-8 (IL-8), interleukin-15 (IL-15), and monocyte chemoattractant protein-1 (MCP-1) are markedly elevated, mirroring the cytokine storm observed in severe SARS-CoV-2-induced pneumonia." (PMID 41573583, 2025).
acute lymphoblastic leukemia (14 papers, 2010 to 2025). Leukemia with an acute onset, characterized by the presence of lymphoblasts in the bone marrow and the peripheral blood. "Two studies showed that rs10519613 in IL15 was associated with the risk of minimal residual disease (MRD) in pediatric acute lymphoblastic leukemia." (PMID 35372081, 2022). "Previous studies revealed that five SNPs in IL-15, rs10519612, rs10519613, rs35964658, rs17007695 and rs17015014, were significantly associated with childhood Acute Lymphoblastic Leukemia (ALL) treatment response." (PMID 21049047, 2010). "However, recent studies have shown that in animal models of CAR-NK cells co-expressing IL-15 in treating acute lymphoblastic leukemia, mice treated with CAR-NK cells can cause systemic toxicity." (PMID 37404752, 2023). "A clinical trial concerning adult acute lymphoblastic leukaemia even specified that higher IL-15 concentration was significantly associated with a poorer outcome and decreased survival rates compared to decreased serum concentrations of IL-15 in the control group of normal healthy individuals." (PMID 32929618, 2021). "Moreover, single nucleotide polymorphisms in the IL15 gene have been associated with risk of developing adult acute lymphoblastic leukemia." (PMID 31740623, 2019). "In adults with acute lymphoblastic leukemia (ALL), IL-15 overexpression has been associated with decreased survival, possibly due to the direct effect of soluble and receptor-bound IL-15 on tumor growth and immune escape." (PMID 38535413, 2023). "This protocol evaluated the impact of two training routines on the regulation of IL-15 and the effect on the overall survivorship of patients with acute lymphoblastic leukemia during the first month of treatment (induction)." (PMID 38535413, 2023). "Recent studies have shown that after CAR-NK cells co-express IL-15, mice treated with the CAR-NK cells can cause systemic toxicity in animal models of acute lymphoblastic leukemia." (PMID 37404752, 2023). "CIK cells stimulated by IL-15 exhibited an enhanced cytotoxic activity against acute lymphoblastic leukemia and lymphoma cell lines, as well as against primary acute myeloid and defined lymphoblastic leukemia cells." (PMID 25196601, 2014). "Clinically, the transgenic expression of membrane IL-15 was first evaluated in a patient with B-cell acute lymphoblastic leukemia (B-ALL) after the failure of the first two CD19-CAR T and CD22-CAR T cell therapies." (PMID 35806311, 2022). "Additionally, blasts from B cell precursor (BCP)-acute lymphoblastic leukemia (ALL) release multiple cytokines and exosomes containing IL-15." (PMID 38726015, 2024). "We previously reported that NOD.Scid mice lacking interleukin-15 (IL-15), or IL-15 receptor alpha-chain, develop T-acute lymphoblastic leukemia (T-ALL)." (PMID 36765626, 2023). "IL-15 is a proinflammatory myokine essential for activating NK cells and CD8+ T lymphocytes, and its overexpression has been related to reducing overall survivorship in patients with acute lymphoblastic leukemia (ALL)." (PMID 38535413, 2023).
malaria (14 papers, 2009 to 2025). Malaria is a serious and sometimes fatal disease caused by a parasite that commonly infects a certain type of mosquito which feeds on humans. "Mice genetically deficient in IL-15 showed delayed clearance of P. chabaudi during experimental murine malaria." (PMID 36839438, 2023). "In line with our previous work showing that human NK cells secrete minimal IL-10 with IL-15 treatment alone, we observed that less than 1% of malaria-naive and malaria-experienced NK cells release IL-10 under these conditions." (PMID 40337867, 2025). "NK cells from malaria-naive individuals were also incubated with IL-15 and IL-21 for 6 days, where the proportion of IL-10 production is approximately 2%." (PMID 40337867, 2025). "The results show that in early malaria, selected immune response-related genes were up-regulated including α β and γ interferon-related genes, as well as genes of IL-15, CD36, chemokines (CXCL10, CCL2, S100A8/9, CXCL9, and CXCL11), TRAIL and IgG Fc receptors." (PMID 24188121, 2013). "By contrast, malaria antigen with IL-2+IL-15 augmented four of 21 (19%) in the exposed sensitized group and two of 17 (11%) in the not-exposed children." (PMID 19636353, 2009). "Exposed not sensitized children had evidence for prenatal immune experience demonstrated by increased IL-10 production and partial reversal of malaria antigen-specific hyporesponsiveness with IL-2+IL-15, indicative of immune tolerance." (PMID 19636353, 2009). "Additionally, we found that secretion of IL-10 by human malaria-naive NK cells is induced in vitro by cytokines IL-15, IL-21, and IL-12." (PMID 40337867, 2025). "Following cytokine stimulation with IL-15 and IL-21, IL-10 release from NK cells was substantially greater from malaria-experienced individuals in both ADCC (~10-fold increase) and natural cytotoxicity assays (~5-fold increase) that occurred in the presence of IL-12." (PMID 40337867, 2025). "The significantly enhanced humoral responses and protection detected after immunization with the MVA-CSP/IL15 vaccine suggest that this IL-15 expressing MVA construct could be considered in the development of future malaria immunization strategies." (PMID 26505634, 2015). "Thus, MVA-based, IL-15 coexpressing candidate malaria vaccines may have an impact on malaria-related morbidity and mortality in endemic areas by reducing levels of blood-stage parasites despite an inability to induce sterile immunity." (PMID 26505634, 2015). "Malaria coinfections with bacteremia were characterized by distinct cytokine profiles, including elevated IFN-γ, IFN-α, IL-4, IL-7, IL-12, IL-15, and IL-17 levels and decreased TNF levels, indicating a strong cytokine response." (PMID 36716305, 2023). "The exploration of potential adjuvanticity of IL-15 to combat various diseases including HIV, tuberculosis, and malaria is underway." (PMID 33953717, 2021). "Although IL-15 is known to induce production of IL-17 from CD4+ T cells, plasma IL-17 was suppressed in malaria monoinfected children and similar in the other groups." (PMID 27418744, 2016). "Here we describe the development and characterization of a novel modified vaccinia virus Ankara (MVA)–based malaria vaccine which co-expresses the Plasmodium yoelii circumsporozoite protein (CSP) and IL-15." (PMID 26505634, 2015). "NK cells from malaria-naive individuals incubated in IL-15 alone for 6 days were used as a negative control for IL-10 production." (PMID 40337867, 2025). "The subgroup IL-15, IL-17 and IL-4 was negatively correlated to the cohort containing IL-6, IL-1Ra MIP-1β, IL-7 and IP-10, which, interestingly, has been shown to be a marker for different infections including malaria and dengue fever." (PMID 34299123, 2021).
malaria (continued). "Regarding the individual biomarkers, we found pro-inflammatory immune mediators increased in malaria patients with levels of IL-6 and IL-8 higher in CM compared to NCM individuals, and of eotaxin, IL-15, MCP-1 and TNFα elevated in deceased compared to survivors of CM." (PMID 27168977, 2016). "The inverse association between parasitemia and elevated levels of IL-1β, IL-1Ra, IL-12, IL-15, IL-17, IFN-γ, and IFN-α in G[−] coinfected children, compared to malaria monoinfection, suggests that this profile may favor induction of antiparasitic activities." (PMID 27418744, 2016). "In addition, both coinfected groups had increased IL-4, IL-5, IL-7, IL-12, IL-15, IL-17, IFN-γ, and IFN-α and decreased TNF-α relative to malaria alone." (PMID 27418744, 2016). "Significantly increased levels of IFN-α, IL-15, and IL-17 were reported in coinfections compared to malaria monoinfection, whether Gram-positive or Gram-negative bacteremia coinfections." (PMID 36716305, 2023). "Similarly, IL-8, IL-6, IL-15 and MCP-1 were reported as increased during malaria." (PMID 27168977, 2016). "In contrast to TNFα, IL-6, IL-8, IL-15 and MCP-1, eotaxin was not often mentioned in previous malaria studies." (PMID 27168977, 2016).
type 1 diabetes (14 papers, 2013 to 2025). "The allele A of this IL15 SNP was also correlated with the risk of type 1 diabetes." (PMID 39844838, 2024). "At 3.5 d, there was wide down-regulation of apoptosis pathways, including type I diabetes mellitus signaling, IL-15 production and IL-15 signaling." (PMID 23341980, 2013). "In vitro treatment with 1,25(OH)2D3 reduced proinflammatory cytokines (IL-6, CCL-2, IL-23A, IL-15) whereas anti-inflammatory cytokines (IL-10 and PD-L1) rose both in APS-type 1 diabetes and APS-Addison ́s disease." (PMID 33365026, 2020).